MET (MET proto-oncogene, receptor tyrosine kinase)
Diseases named in the same sentence as MET in open-access papers (continued):
Sharing a sentence is not in itself a finding about the gene and the disease.
tumor (continued). "HGF/c-MET activates multiple cell signaling pathways leading to tumor cell proliferation, such as the RAS, PI3K, or Wnt/β-catenin pathway." (PMID 37511344, 2023). "The HGF and MET genes are expressed in human glioma and medulloblastoma, where their increased relative abundance frequently correlates with tumor grade, tumor blood vessel density and poor prognosis." (PMID 36672409, 2023). "Tissue samples from nine patients were available for c-MET expression analysis via IHC (excluding 1 non-tumor patient)." (PMID 36184713, 2023). "Previous studies have shown that c-MET activation occurs in 20–44% of HCC patients, and increased expression of c-MET is associated with poor tumor differentiation, augmented intrahepatic metastases, and poor prognosis." (PMID 37500626, 2023). "BATF2 has been previously reported as a novel tumor suppressor gene that inhibits the growth of cancer cells through repression of hepatocyte growth factor receptor/MET signaling." (PMID 37777155, 2023). "It was found that iCAF-derived hepatocyte growth factors promote CCA tumor growth through interaction with tumor cells, inducing expression of MET." (PMID 36980203, 2023). "In murine tumor models where HGF from hepatic stellate cells (HSC)-derived CAFs or MET from tumor cell sources was deleted using Lrat-Cre-transgenic mice, a significant reduction in tumor invasiveness and size was observed." (PMID 37919751, 2023). "Clinical trials indicate that effective MET inhibitors require ongoing MET activation in tumor growth." (PMID 37779207, 2023). "Savolitinib is a selective and potent c-MET inhibitor that showed synergistic tumor inhibition in c-MET amplified CRC PDX preclinical models in combination with the anti-VEGF inhibitor apatinib." (PMID 38269272, 2023). "MET, ERBB2, VEGFR2, PFGFR, and EGFR, among others, represent acknowledged targets of semaphorins often associated with tumor progression or poor prognosis." (PMID 38067240, 2023). "In this study, we addressed this challenge with a large‐scale screening of 79,803 patients across 27 tumor types, which led to the detection of 155 putative MET fusions from DNA‐based genomic profiles of 122 patients." (PMID 37326363, 2023). "We observed that patients with tumor samples showing strong (score 3+) c-MET IHC staining had a shorter mOS than those with weak or moderate (score 1+ ~ 2+) c-MET IHC staining (5.7 vs. 24.8 months, p = 0.013)." (PMID 36969059, 2023). "The multitargeted TKI cabozantinib has shown antitumor activity against tumor cells expressing activated (phosphorylated) receptors MET and AXL (P-MET and P-AXL), including sunitinib-resistant human RCC cells." (PMID 36982721, 2023). "Through MET signaling, the tumor survives under hypoxic conditions, fights immune attacks, resists radiotherapy and chemotherapy, and sustains the clonal expansion occurring after resistance to targeted treatments." (PMID 37345079, 2023). "These can be caused by activating mutations in the kinase domain or, more commonly, MET gene amplification, and can lead to HGF‐independent cellular proliferation and tumour growth." (PMID 36799689, 2023). "Many studies investigated the tumor-biological and clinicopathological characteristics of MET-positive GCs." (PMID 36260159, 2023). "A cut point of >50% of tumor cells staining moderately or strongly has been associated with treatment benefit in NSCLC and is often used as a standardized cut-off of MET overexpression." (PMID 37046637, 2023). "We first confirmed target inhibition by tepotinib by measuring p-MET levels in tumor samples by immunoblot: p-MET was detected in the tumor and the tumor-bearing right hemisphere." (PMID 36915128, 2023). "As of today, NGS testing has been expanded to comprehensive genomic profiling (CGP), and to different tumor types, as MET amplification is a rare oncogenic driver across all solid tumor types." (PMID 37046637, 2023).
tumor (continued). "Concurrent administration of sunitinib (VEGFR and PDGFR receptor tyrosine kinases inhibitor (RTKI)) and HGF/c-MET inhibitors effectively inhibited angiogenesis and tumor growth." (PMID 36959862, 2023). "Tepotinib inhibits the phosphorylation of MET and subsequent signaling pathways, leading to the inhibition of growth and migration of tumor cells." (PMID 37901797, 2023). "Therapies targeting c-MET and PD-L1 using diabodies showed a superior tumor control capacity compared to combination therapy of two antibodies alone in mouse tumor models." (PMID 37620318, 2023). "In this comprehensive review, we analyze and compare the potential impact of the Hh pathway on the tumor microenvironment (TME) in HGF/c-MET-driven tumor models, as well as the interplay between different cell types." (PMID 37919751, 2023). "We screened 79,803 patients across 27 tumor types and detected 155 putative MET fusions from 122 patients, resulting in an overall prevalence of 0.15%." (PMID 37326363, 2023). "AXL also forms a complex with the non-receptor tyrosine kinase SRC and mediates the enhanced activity of MET in an HGF-independent manner to facilitate tumor migration and invasion in ccRCC." (PMID 36831657, 2023). "Histological analysis confirmed the presence of a large number of tumor nodules in the lungs of mice injected with wild-type cells, while nodules originated from the injection of MET−/− A549 cells were lower in number and smaller in size." (PMID 37345079, 2023). "This unique activation profile of MET opens new avenues for future research, particularly to explore the implications of its long-lasting response in both physiology and tumor biology." (PMID 37760640, 2023). "MET, ERBB2, VEGFR2, PFGFR, and EGFR, among others, represent acknowledged targets of semaphorins that are often associated with tumor progression or poor prognosis." (PMID 38067240, 2023). "Flow cytometry-based analysis of the GL-261 tumor-bearing hemisphere demonstrated that MET is expressed by tumor and brain parenchymal cells." (PMID 36915128, 2023). "Using Formalin-Fixed Paraffin-Embedded (FFPE) samples they detected the relative overexpression of c-MET protein in tissue sections in disease progression and found that c-MET overexpression was specific to MAPKi-resistant tumor cells." (PMID 37174072, 2023). "Cabozantinib is a receptor TKI with targets that include MET (c-MET), VEGFR2, RET, AXL, KIT, and TIE-2, which are implicated in tumor growth, metastasis, and angiogenesis." (PMID 36595123, 2023). "In this way, we evaluated the contribution of the HGF/MET axis to cancer cell dissemination independently of its direct activities in cells of the tumor microenvironment." (PMID 37345079, 2023). "Capmatinib (c-MET-specific inhibitor) plus pitavastatin (HMGCR inhibitor) synergistically inhibited tumor growth and served as a novel treatment regimen in oral and esophageal cancer." (PMID 36646686, 2023). "Similar findings were observed for the c-MET IHC distribution patterns; patients with tumor samples showing a diffuse pattern had shorter mOS than those with samples showing a focal pattern (3.8 vs. 27.6 months, p = 0.036)." (PMID 36969059, 2023). "Different molecular mechanisms counteracting MET inhibition activity have been described in the literature as a result of the feedback loops responsible for the regulation of drug targets in tumor cells." (PMID 36982721, 2023). "High MET expression in cancer tissue was considered to correlate to advanced tumour status, lymph node metastasis and poor survival." (PMID 35953652, 2023). "HGF is abundantly expressed in a critical TME component known as CAFs, while its receptor, c-MET, is highly expressed in tumor cells." (PMID 37919751, 2023). "In prostate and pancreatic cancer, both HGF and MET genes are reported to be preferentially expressed in stem-like tumour cells." (PMID 37368660, 2023).
tumor (continued). "To investigate the potential therapeutic strategies for c-MET/sgp53 tumors, we developed a stably passaged cell line (MP cells) derived from a c-MET/sgp53 HCC by serial passaging of tumor cells from mouse to mouse." (PMID 37500626, 2023). "Mechanisms of its antitumor activity are considered via anti-angiogenesis and/or direct inhibition of kinase signals associated with tumor growth, including CSF1R, MET, and PDGFRs9,10,12." (PMID 37258621, 2023). "We were also able to demonstrate, by immunohistochemistry, the expression of MET in 63% of the tumor tissue samples analyzed, with the majority demonstrating a relatively low expression profile." (PMID 37104404, 2023). "This research has provided a comprehensive analysis of the cross-talk between the primary c-MET and Hh pathways within tumor cells." (PMID 37919751, 2023). "In EWS, modest to high MET cytoplasmic/membranous expression is detected in the majority of tumor samples and is significantly correlated with a poor overall survival." (PMID 36839989, 2023). "We also investigated the effects of HER3‐ and/or MET‐KO on in vivo tumor growth by xenografted SW1116 cells in nude mice." (PMID 36751113, 2023). "HGF as a ligand binds to c-MET on the surface of tumor cells and can lead to downstream signaling pathways." (PMID 38264122, 2023). "That study explored the KRAS-specific effect on triggering tumour cell invasion upon fibroblast stimulation through the HGF-c-MET axis." (PMID 38087207, 2023). "Contrastingly, HSP90 simultaneously supports the maturation of cancer-related proteins, including mesenchymal epithelial transition factor (MET) within tumor cells." (PMID 37547755, 2023). "METamp is thought to be a mechanism of overexpression of the MET receptor and its constitutive, ligand-independent activation, thereby dysregulating the MET pathway and promoting tumor growth." (PMID 36999986, 2023). "The metastatic potential of MET−/−A549 cells was assessed in vivo by measuring their ability to generate tumor nodules in the lungs after intravenous injection in hHGF-KI mice." (PMID 37345079, 2023). "We found that one-time injection of MET-CAR.CD28ζ T cells completely inhibited tumor growth as compared with MET-CAR∆ T cells." (PMID 37779207, 2023). "Moreover, the tumor-stroma interaction was associated with higher activation of the hepatocyte growth factor/MET-mediated PI3K/AKT signaling pathway and epithelial-mesenchymal transition process, supporting the hypothesis of fibroblast-involved resistance to EGFR TKI treatment." (PMID 36647832, 2023). "MET gene is involved not only in the proliferation, differentiation and invasion of various human tumor cells, but also in the resistance of anti-tumor drugs." (PMID 35978812, 2022). "Cabozantinib inhibits tumor angiogenesis while targeting the hepatocyte growth factor receptor protein (MET), which modulates tumor immunity." (PMID 36142591, 2022). "Comprehensive genomic profiling of this patient’s tumor revealed high MET gene amplification resulting in the use of capmatinib, a highly potent and selective inhibitor of the MET receptor." (PMID 35129063, 2022). "Sorafenib inhibits angiogenesis, resulting in hypoxia inside tumors, which in turn increases the production of hepatocyte growth factor (HGF) and expression of c-MET in tumor cells." (PMID 35546143, 2022). "Different in vitro studies have demonstrated a concentration-dependent inhibition by crizotinib of tyrosine phosphorylation mediated by ALK, ROS1, and MET in different tumor cell line-based assays." (PMID 35565287, 2022). "Previous studies have shown that MET, encoded by the HGFR gene, NRAS, a known RAS family oncoprotein, and NFE2L2 promote tumor growth and metastasis in HCC, and their somatic mutation can cause liver carcinogenesis." (PMID 34543520, 2022).
tumor (continued). "In our present study, bioinformatics analysis and experimental method verification were used in combination to confirm that miR-495 directly targeted HGF and c-MET mRNA in CRC cells as well as in cetuximab-treated CRC patients whose tumours had progressed." (PMID 34976187, 2022). "In PC, increasing of MET transcription leads to c-Met overexpression, and c-Met increasing promotes tumor genesis and development through a variety of mechanisms." (PMID 35978812, 2022). "In contrast to RPTEC, global EGFR and MET activities showed less activity in the FLCN-negative UOK257 tumor cell line when compared with the FLCN-restored UOK257-2, even though EGFR and MET emerge as significantly important pathways in each cell model." (PMID 35863698, 2022). "In these cell contexts, its anti-tumor function has been correlated with the inhibition of molecular targets other than MET." (PMID 35574376, 2022). "As a proto-oncogene, MET mediates tumor cell proliferation, invasion, angiogenesis, chemotherapy resistance, epithelial-mesenchymal transformation." (PMID 35978812, 2022). "MET has been found to promote tumour development and metastasis by binding to hepatocyte growth factor (HGF)." (PMID 35711496, 2022). "In contrast, MET amplification has been reported to coexist with HER2 amplification in several tumor samples." (PMID 35954414, 2022). "CT053PTSA is a potent inhibitor of MET, AXL, VEGFR-2, FMS-like tyrosine kinase 3 (FLT3) and MERTK, all of which have been implicated in tumor pathogenesis." (PMID 36341335, 2022). "MET amplification was present in 15% of tumor samples from patients who were relapsing on next-generation ALK inhibitors, compared to 12% and 22% of tumor biopsies from patients who were progressing on second-generation inhibitors or lorlatinib, respectively." (PMID 36499382, 2022). "The migration and promotion of cell survival by MET activation-induced cell dynamics is the basis for the mechanisms of invasiveness, metastasis and drug resistance of tumor cells." (PMID 36502446, 2022). "One small-molecule MET receptor tyrosine kinase inhibitor, tivantinib has the ability to promote the apoptosis of MET-positive tumour cell lines." (PMID 35711496, 2022). "qPCR analysis of c-MET mRNA in NB tumor samples found a correlation between increased c-MET expression and later clinical stage." (PMID 36034555, 2022). "Immunohistochemistry (IHC) staining showed that the expression of Ki-67, MET, and eIF4G1 was much lower in circTMTC1 silence tumor tissues than that in sh-NC control tumor tissues." (PMID 35301291, 2022). "On the other hand, part of the tumor can recruit the protein tyrosine phosphatase 1B by strengthening MET/VEGFR2 heterozygote to inhibit tumor migration." (PMID 35860704, 2022). "Pharmacological c-MET inhibition in OS has been shown to decrease malignant behavior of OS cells in culture, and to suppress in vivo xenograft tumor growth." (PMID 36034555, 2022). "Tumor-derived factors induce the expression of the mesenchymal–epithelial transition tyrosine kinase receptor (MET) in neutrophils." (PMID 36555469, 2022). "In order to demonstrate the molecular mechanism of INC280-PFCE NPs to inhibit tumor growth, survival, and invasion, we analyzed the expression levels of phospho-MET and its downstream effectors using western blot." (PMID 36457016, 2022). "This Gα12-induced downregulation of miR-122 increased expression of its target c-MET, which blocked apoptosis and induced tumor growth." (PMID 34689178, 2022). "c-MET, encoded by MET, plays a central role in promoting tumor invasive growth and driving cancer progression towards metastasis." (PMID 36109787, 2022). "Downregulation and/or inhibition of c-MET significantly decreased growth, migration, and invasion as well as induced apoptosis of tumor cells in a variety of tumor models." (PMID 35069735, 2022).
tumor (continued). "Given the large amount of preclinical data convincingly proving the causative role of HGF in drug resistance, targeting stromal HGF (or its tyrosine-kinase receptor MET expressed on tumor cells) is predicted to counteract tumor resistance." (PMID 36324182, 2022). "In agreement with our cell line findings, GSEA results show a positive enrichment of KRAS-mediated gene sets in the transcriptomes of METΔex14-mutant tumours compared to those with high-grade wildtype MET amplification." (PMID 35326531, 2022). "In a subset of patients, HB tumors were compared to normal liver tissue (from the same patient, n = 5) and c-MET mRNA levels were found to be upregulated in HB tumor samples compared to healthy liver tissue." (PMID 36034555, 2022). "Downregulation of c-MET in RMS cell lines decreased both in vivo tumor growth and bone marrow engraftment." (PMID 36034555, 2022). "Assessing tumor tissue as well as primary cells both naïve and resistant to systemic drugs, we illustrate the most promising role of c-MET." (PMID 35406455, 2022). "Hitherto, targeting specifically the MET disulfide isomerase activity in a therapeutic window can lead to the impairment of MET functions and tumor growth." (PMID 36293286, 2022). "Mechanistically, INC280-PFCE NPs effectively inhibited tumor survival, proliferation and migration by inhibiting the c-MET signaling pathway and its major downstream factors." (PMID 36457016, 2022). "Higher levels of phosphorylated c-MET were correlated with tumor recurrence and poor prognosis in the SHH subgroup of MB." (PMID 36034555, 2022). "In our analysis, c-MET was detectable in 95.7% of samples, whereas augmented expression of c-MET in tumor tissue was significantly associated with and independently predicted for unfavorable DSS." (PMID 35406455, 2022). "We observed that combined targeting of PDAC cell PD-1 and MET resulted in substantial direct tumor cell cytotoxicity and growth inhibition in PDAC cell lines, patient-derived organoids, and patient-derived xenografts independent of cytotoxic immune responses." (PMID 35804822, 2022). "She underwent a biopsy on neck lymph node before CT053PTSA treatment, results showed that tumor tissue was MET overexpressed by immunohistochemistry (IHC)." (PMID 36341335, 2022). "In approximately 70% of LUAD tumor tissue the MET gene is significantly overexpressed, moreover, overexpression of MET in plasma of patients with LUAD is a known phenomenon." (PMID 36544145, 2022). "The multivariate regression analysis confirmed tumor stage and c-MET expression as independent prognostic factor for both DFS and BCSS." (PMID 36498560, 2022). "In the U87 tumor-bearing animal model, dP@gVLP/RNAic-MET was found to penetrate the BBB with high efficiency and cause significant tumor growth suppression, particularly when paired with temozolomide (TMZ)." (PMID 36714624, 2022). "Remarkably, examining circulating tumor DNA, it was possible to find MET amplification even before the recurrence became clinically evident." (PMID 35582524, 2022). "As expected, circTMTC1 silence reduced circTMTC1 expression and MET mRNA level and increased miR-495 expression in subcutaneous tumor tissues." (PMID 35301291, 2022). "MET has been shown to be actively expressed in a variety of tumor cells, and is closely related to the growth and proliferation of tumor cells." (PMID 36502446, 2022). "In pancreatic cancer, the tumor-released exosomal circRNA PDE8A promotes aggressive growth through the miR-338/MACC1/MET pathway." (PMID 35505392, 2022). "The literature has shown that MET deletion in neutrophils leads to the enhancement of tumor growth and metastasis." (PMID 35986321, 2022). "Cabozantinib is a multiple-receptor TKI targeting MET (c-MET), VEGFR2, RET, AXL, KIT, and TIE-2, all implicated in tumor growth, metastasis, and angiogenesis." (PMID 36551927, 2022).